PDCD1 (programmed cell death 1)
Diseases named in the same sentence as PDCD1 in open-access papers (continued):
Sharing a sentence is not in itself a finding about the gene and the disease.
periodontitis (2 papers, 2021 to 2024). An acute or chronic inflammatory process that affects the tissues that surround and support the teeth. "We also found PDCD1 was highly upregulated in the CD4_CTLA4 cluster from periodontitis, which indicates that PD-1 pathway may contribute to the protective effect of Treg in disease stage." (PMID 34566966, 2021).
tauopathy (2 papers, 2024 to 2025). Neurodegenerative disorders involving deposition of abnormal tau protein isoforms (tau proteins) in neurons and glial cells in the brain. "In a mouse model of tauopathy, depleting T cells or using an immune checkpoint blockade (PDCD1) reduced neurodegeneration, which agrees with other studies in models of neurodegenerative disease, suggesting a provocative hypothesis that T cells could be directly causing neurodegeneration in AD." (PMID 38867294, 2024).
VKH syndrome (2 papers, 2009 to 2019). "Our present study was designed to investigate the association of PDCD1 single nucleotide polymorphisms (SNPs) including PD-1.3, PD-1.5, and PD-1.6 with VKH syndrome in a Chinese Han population." (PMID 19234630, 2009). "It is not clear whether this association is present in other ethnic VKH patients and whether other PDCD1 polymorphisms are associated with the susceptibility to VKH syndrome." (PMID 19234630, 2009).
Achalasia (1 paper, 2023). A disorder of esophageal motility characterized by the inability of the lower esophageal sphincter to relax during swallowing and by inadequate or lacking peristalsis in the lower half of the body of the esophagus. "Besides, many co-inhibitory molecules, including PDCD1, HAVCR2, LAG3, ICOS, PRDM1, and MAF, were markedly downregulated in TRM, supporting an activated cell state in achalasia." (PMID 37542039, 2023).
acute coronary syndrome (1 paper, 2023). Signs and symptoms related to acute ischemia of the myocardium secondary to coronary artery disease. "Further, stimulation of PBMCs (peripheral blood mononuclear cells) with LL-37 was associated with reduced programmed cell death protein 1 (PDCD1) mRNA expression in patients with acute coronary syndrome." (PMID 37090695, 2023).
acute GVHD (1 paper, 2023). "The presence of the LAG3 rs870849 TT genotype was associated with an increased risk of severe acute GVHD independently of the PDCD1 rs36084323 genotype." (PMID 36742309, 2023). "Multivariate analysis confirmed that LAG3 rs870849 TT genotype of the donor was an independent risk factor for a higher incidence of acute GVHD, independently of the PDCD1 genotype (p: 0.031; HR: 1.76, 95%CI: 1.05 – 2.94)." (PMID 36742309, 2023). "When combining the LAG3 rs870849 and the PDCD1 rs36084323 genotypes of the donor, three genetic groups were well defined, allowing a good stratification of the risk of acute GVHD, TRM, OS and DFS." (PMID 36742309, 2023).
anemia (1 paper, 2025). A reduction in the number of red blood cells, the amount of hemoglobin, and/or the volume of packed red blood cells. "Programmed cell death 1 (PD-1) inhibitor therapy for lung adenocarcinoma may induce rare but severe hematologic adverse events, including severe anemia." (PMID 40640098, 2025).
aneuploidy (1 paper, 2025). Chromosomal disorder consisting of the presence a chromosomal abnormality in which there is an addition or loss of chromosomes within a set. "In addition, it was also found that some immune checkpoint genes (PDCD1, HAVCR2, TIGIT, LAG3) had high expression in high-risk group, which was related to a higher TIDE and aneuploidy scores than in the low-risk group." (PMID 39950044, 2025).
angioimmunoblastic T-cell lymphoma (1 paper, 2024). A mature T-cell non-Hodgkin lymphoma, characterized by systemic disease and a polymorphous infiltrate involving lymph nodes and extranodal sites. "Angioimmunoblastic T-cell lymphoma (AITL) is a peripheral T-cell lymphoma characterized by a T follicular helper cell phenotype expressing PD-1 (programmed cell death-1)." (PMID 38983865, 2024).
atrial fibrillation (1 paper, 2025). A disorder characterized by an electrocardiographic finding of a supraventricular arrhythmia characterized by the replacement of consistent P waves by rapid oscillations or fibrillatory waves that vary in size, shape and timing and are accompanied by an irregular ventricular response. "This study aimed to investigate the association between peripheral blood programmed cell death 1 (PD-1)/programmed death ligand 1 (PD-L1) expression and atrial fibrillation (AF) in the Han and Kazakh populations of Xinjiang." (PMID 41367015, 2025).
autism (1 paper, 2016). Persistent deficits in social interaction and communication and interaction as well as a markedly restricted repertoire of activity and interest as well as repetitive patterns of behavior. "We analyzed the Simons Simplex Collection of 2508 parent-offspring autism trios using VARPRISM, replicating 44 genes previously implicated in autism susceptibility and identifying 20 additional candidate genes, including MYO1E, KCND3, PDCD1, DLX3, and TSPAN4 (false discovery rate < 0.3)." (PMID 27562213, 2016).
autoimmune myocarditis (1 paper, 2022). Autoimmune myocarditis is an autoimmune disease that affects the heart. "It has been reported that the deletion of Pdcd1 causes autoimmune myocarditis, and that Pdcd1 protects against inflammation and myocyte damage in the heart." (PMID 35190965, 2022). "However, the inhibition of Pdcd1 activity can produce a wide spectrum of immune-related adverse events such as autoimmune myocarditis and dilated cardiomyopathy." (PMID 35190965, 2022).
brain glioma (1 paper, 2019). A malignant glioma that involves the brain. "Brain glioma treatment with checkpoint inhibitor antibodies to cytotoxic T-lymphocyte-associated antigen 4 (a-CTLA-4) and programmed cell death-1 (a-PD-1) was largely unsuccessful due to their inability to cross blood–brain barrier (BBB)." (PMID 31462642, 2019).
Candidemia (1 paper, 2016). A form of invasive candidiasis where species of CANDIDA are present in the blood. "CD4 and CD8 T cells from patients with Candidemia expressed markers typical of T cell exhaustion as indicated by either increased percentages of or increased MFI for programmed cell death 1 (PD-1) or its ligand (PD-L1)." (PMID 26786705, 2016).
cardiomyopathy (1 paper, 2023). A disease of the heart muscle or myocardium proper. "In contrast the deletion of Pdcd1 (encoding PD-1) in Balb/c mice causes cardiomyopathy due to the development of autoantibodies against troponin I25." (PMID 37684243, 2023).
Chagas disease (1 paper, 2013). A parasitic infection caused by Trypanosoma cruzi. "Genotype and allele frequencies of polymorphisms at the CTLA-4 and PDCD1 genes in patients with Chagas disease and healthy controls." (PMID 24205212, 2013).
cholangitis (1 paper, 2023). An acute or chronic inflammatory process affecting the biliary tract. "A rare but potentially severe IR adverse event is IR-cholangitis, which is mostly induced by anti-programmed cell death 1 (PD1) antibodies and is often corticosteroid-resistant." (PMID 37728439, 2023).
chordoma (1 paper, 2023). Chordomas are rare malignant tumors arising from embryonic remnants of the notochord in axial skeleton. "One of the primary ways in which chordoma lesions exhibit immunosuppression is through the identification of CTLA4 and PDCD1 expression on Tregs." (PMID 37784253, 2023). "Despite the elevated proportion of Tregs observed in recurrent chordomas, the cells exhibited significant expression of TIGHT, CTLA4, PDCD1, ENTPD1 and HAVCR2, indicating the immunosuppressive nature of Tregs." (PMID 37784253, 2023).
CMV infection (1 paper, 2021). "Five SNPs (rs36084323, rs5839828, rs41386349, rs6705653, and rs2227982) in PDCD1 gene are associated with the risk for relapse, mortality, CMV infection, and GVHD." (PMID 34671352, 2021). "One SNP (rs6705653 in PDCD1) and four SNPs (rs36084323, rs41386349, rs6705653, and rs2227982 in PDCD1) were found to associate with CMV infection in patients with AML and ALL, respectively." (PMID 34671352, 2021). "The C allele of rs36084323, A allele of rs41386349, and G allele of rs2227982 in PDCD1 gene also associated with a higher risk for CMV infection (allele model: p = 0.0265, 0.0356, and 0.0252, respectively)." (PMID 34671352, 2021). "In this study, we explored the association between donor SNPs of co-stimulatory genes (CTLA4, CD28, TNFSF4, and PDCD1) and the mortality, CMV infection, GVHD, and relapse of their corresponding recipients in the Taiwanese population." (PMID 34671352, 2021). "With the importance of co-stimulatory signals in the immune system and transplantation tolerance, the associations of the four co-stimulatory genes including CTLA4, TNFSF4, CD28, and PDCD1 with the mortality, relapse, CMV infection, and GVHD after HSCT were analyzed in this study." (PMID 34671352, 2021). "In this study, we investigated further whether these is an association between 34 donor SNPs in the four co-stimulatory genes (TNFSF4, CTLA4, CD28, and PDCD1) and the occurrence of adverse outcomes (mortality, relapse, CMV infection, and GVHD) for patients with AML and ALL." (PMID 34671352, 2021).
delirium (1 paper, 2023). A disorder characterized by confusion; inattentiveness; disorientation; illusions; hallucinations; agitation; and in some instances autonomic nervous system overactivity. "Moreover, the last pembrolizumab (anti‐programmed cell death 1 antibody [anti PD‐1]) was given 4 months ago and the possibility of psychiatric disorders including delirium associated with anti PD‐1 is reported to be 1.91% and is the lowest in immune checkpoint inhibitors." (PMID 38868734, 2023).
diabetes ketoacidosis (1 paper, 2025). "Immune checkpoint inhibitor-related diabetes ketoacidosis (ICI-DKA) and hypothyroidism are rare but serious adverse events of Anti-programmed cell death-1 (anti-PD-1) therapy, previously unreported in patients with EAC receiving tislelizumab." (PMID 40951340, 2025).
diarrhoea (1 paper, 2022). "Moreover, rs5839828 of PDCD1 was associated with diarrhoea based on the additive model (p=0.046)." (PMID 36389676, 2022).
dysgerminoma (1 paper, 2025). A malignant germ cell tumor characterized by the presence of a monotonous primitive germ cell population. "TIGIT, IDO1, CTLA4, and PDCD1 were specifically upregulated in dysgerminomas." (PMID 40621458, 2025).
encephalitis (1 paper, 2023). An acute inflammatory process affecting the brain parenchyma. "For LGI1 encephalitis patients (n = 6) and HDs (n = 4), miR-2467-5p expression in PBMCs was negatively associated with the serum levels of PDCD1 (r = −0.867, p = 0.002) and CSF3 (r = −0.721, p = 0.023), but favorably correlated with the serum level of CCL15 (r = 0.746, p = 0.017)." (PMID 37644514, 2023). "Decreased PDCD1 with increased ICAM1 could predict unfavorable prognosis in one-year follow-up for LGI1 encephalitis patients." (PMID 37644514, 2023). "The serum of patients with LGI1 encephalitis had reduced levels of CD28, ICOS-L, PDCD1 (all p < 0.05), and CD86 (p < 0.01), but higher levels of ICOS (p < 0.05) and PD-L2 (p < 0.001) were detected." (PMID 37644514, 2023). "Mechanically, miR-2467-5p significantly induced reduced expression of CSF3 and PDCD1 by binding with their 3`UTR while enhanced CCL15 expression, but not significantly correlated with peripheral blood CD19 + B cell proportion of LGI1 encephalitis patients." (PMID 37644514, 2023). "However, PDCD1 without methylation changes in promoter was significantly lower in PBMCs of LGI1 encephalitis patients compared with HDs." (PMID 37644514, 2023). "The ROC curve also indicated that the combination of PDCD1 and ICAM1 could predict unfavorable prognosis of LGI1 encephalitis patients at one-year follow-up more accurately than either PDCD1 or ICAM1 alone (AUC = 0.936 p = 0.003 vs. AUC = 0.821 p = 0.028; AUC = 0.778 p = 0.052)." (PMID 37644514, 2023). "Then, bioinformatics algorithms uncovered the probable miR-2467-5p binding sites in the 3'untranslated region (UTR) of CSF3' and PDCD1' mRNA, and a negative correlation was found between PDCD1 expression and CCL15 expression in the serum of LGI1 encephalitis patients (r = −0.546, p = 0.013)." (PMID 37644514, 2023).
Erythema (1 paper, 2023). Redness of the skin, caused by hyperemia of the capillaries in the lower layers of the skin. "The reactions of programmed cell death-1 (PD-1) inhibitors were presented, such as fever, rash, erythema with itching, and hair turning black and luster." (PMID 37151866, 2023).
experimental autoimmune encephalomyelitis (1 paper, 2025). An autoimmune demyelinating disease of the central nervous system that is produced experimentally in animals by the injection of homogenized brain or spinal cord in Freund's adjuvant. "In the experimental autoimmune encephalomyelitis mouse model, Pdcd1+ γδ T cells have been implicated in promoting disease pathogenesis." (PMID 40843005, 2025).
Fever (1 paper, 2022). Body temperature elevated above the normal range. "Analyzing the side effects induced by second dose of mRNA vaccines, two SNPs of PDCD1 were found to be associated with fever, namely, rs2227982 (additive, p=0.030; AG+AA vs. GG, p=0.013, OR=0.348, 95% CI." (PMID 36389676, 2022).
gestational trophoblastic neoplasia (1 paper, 2021). "Immune checkpoint blockade (ICB) antibodies targeting programmed cell death ligand-1 (PD-L1) and programmed cell death-1 (PD-1) have improved survival in patients with conventional single agent chemotherapy-resistant gestational trophoblastic neoplasia (GTN)." (PMID 34681187, 2021).
glomerulosclerosis (1 paper, 2022). A hardening of the kidney glomerulus caused by scarring of the blood vessels. "PDCD1 transcript increased with age in microdissected human glomeruli, which correlated with lower estimated glomerular filtration rate and higher segmental glomerulosclerosis and vascular arterial intima-to-lumen ratio." (PMID 35968783, 2022).
Headache (1 paper, 2022). Cephalgia, or pain sensed in various parts of the head, not confined to the area of distribution of any nerve. "= 1.005–2.075) and rs36084323 (CT+TT vs. CC, p=0.041) of PDCD1 were associated with headache." (PMID 36389676, 2022). "Moreover, rs41386349 located in the promoter region of PDCD1 was associated with headache (additive, p=0.038)." (PMID 36389676, 2022).
hepatitis C virus infection (1 paper, 2024). A viral infection caused by the hepatitis C virus. "Some previous studies also indicated that PDCD1, CTLA4, and HAVCR2 polymorphisms were sex-dependently associated with MAC-LD risk, the resolution of hepatitis C virus infection, and the outcomes of HCV infection, respectively." (PMID 38723011, 2024).
hepatopathy (1 paper, 2017). "One patient developed chemotherapy-induced hepatopathy with a programmed cell death-1 (PD-1) inhibitor for the treatment of non-small cell lung cancer." (PMID 28028790, 2017).
histiocytic sarcoma (1 paper, 2025). An aggressive malignant neoplasm with a poor response to therapy, usually presenting as stage III/IV disease. "In canine histiocytic sarcoma, transcriptomic analysis revealed three key genes: PDCD1 (PD-1), overexpressed in tumors with higher T-cell infiltration; SPP1 (osteopontin), linked to immunosuppression; and TXNIP, a suppressed tumor suppressor." (PMID 40725420, 2025).
interstitial lung disease (1 paper, 2020). A diverse group of lung diseases that affect the lung parenchyma. "In this cohort study of 199 patients with advanced nonlung cancers treated with anti–programmed cell death 1 antibody monotherapy, patients with preexisting interstitial lung abnormalities had significantly increased risk of immune checkpoint inhibitor induced–interstitial lung disease." (PMID 33180128, 2020).
intraductal papillary mucinous neoplasms (1 paper, 2020). "The percentage of CD8A-positive T lymphocytes expressing HAVCR2 and/or PDCD1 was lower in cases of intraductal papillary mucinous neoplasms (IPMN) and serous cystadenoma (SC) compared to the percentage observed in PDAC." (PMID 32645996, 2020).
kidney tumors (1 paper, 2025). "On the other hand, higher methylation of PDCD1 and HAVCR2 was found in normal tissues compared to the respective tumors in BRCA, UCEC, kidney tumors, lung tumors, LIHC, and HNSC." (PMID 40076932, 2025).
laryngeal carcinoma (1 paper, 2022). Carcinoma that arises from the laryngeal epithelium. "We found that low-risk laryngeal cancer samples were more sensitive to PDCD1, LAG3, CTLA4, and TIGHT, indicating that fatty acid metabolism is of interest in terms of assessing the TME characteristics in patients with laryngeal cancer." (PMID 36335208, 2022). "We found that laryngeal cancer samples in the low-risk score group were more sensitive to PDCD1, LAG3, CTLA4, and TIGHT." (PMID 36335208, 2022).
leprosy (1 paper, 2018). Leprosy is a chronic infectious disease affecting primarily the skin and peripheral nervous system. "In the immunosuppressive environment like leprosy, upregulation of inhibitory molecules such as cytotoxic T-lymphocyte-associated antigen-4 (CTLA-4) and programmed cell death-1 (PD-1) on T cells and their ligands on APCs which resemble T-cell anergy and exhaustion in leprosy patients." (PMID 30083152, 2018).
liver cirrhosis (1 paper, 2023). "Genes related to senescence (e.g., PTPRC, TIGIT, and TNF) and exhaustion (e.g., PDCD1, CTLA4, LAG3, and TNFRSF9) were highly enriched in CD4+ and CD8 + T cells from the participants with liver cirrhosis." (PMID 37735474, 2023). "We found significantly higher expression of markers of T-cell senescence (e.g., PTPRC, TIGIT, and TNF) and exhaustion (e.g., PDCD1, CTLA4, LAG3, and TNFRSF9) in hepatic CD4+ and CD8 + T cells in participants with NASH or liver cirrhosis than in controls." (PMID 37735474, 2023).
liver fibrosis (1 paper, 2024). "Then we speculate that immune checkpoints might correlate with HSC activation and liver fibrosis and found that SLC1A5 was significantly negatively associated with CTLA4, LAG3, and PDCD1; similarly, SLC7A5 was significantly negatively associated with CTLA4 and LAG3." (PMID 39698464, 2024).
lower respiratory tract infection (1 paper, 2025). "Moreover, programmed cell death 1 (PD-1) protein is elevated in CD8+ T cells in RSV lower respiratory tract infection (LRTI), inhibiting pro-inflammatory cytokine production in activated T cells and further suppressing the T cell response." (PMID 40636105, 2025).
myeloid leukemia (1 paper, 2025). A clonal proliferation of myeloid cells and their precursors in the bone marrow, peripheral blood, and spleen. "PDCD1 mRNA and PD-1 protein expression is higher in CD34+ bone marrow cells of patients with myeloid leukemia (CMML and AML) compared to healthy controls." (PMID 40175626, 2025).
nephrotic syndrome (1 paper, 2022). A collection of symptoms that include severe edema, proteinuria, and hypoalbuminemia; it is indicative of renal dysfunction. "Furthermore, we searched the Nephroseq database for PDCD1 mRNA expression in human microdissected glomeruli from patients undergoing indication kidney biopsies enrolled in the Nephrotic Syndrome Study Network (NEPTUNE)." (PMID 35968783, 2022).
non-melanoma skin carcinoma (1 paper, 2021). "Immunotherapy, targeting specific immune checkpoints including cytotoxic T-lymphocyte antigen 4 (CTLA-4), programmed cell death 1 (PD1), and programmed cell death ligand 1 (PD-L1) has revolutionized the treatment of both locally advanced and metastatic melanoma and non-melanoma skin cancer." (PMID 34291066, 2021).
ophthalmoplegia (1 paper, 2021). Weakness or paralysis of at least one of the muscles controlling the movement of the eye. "Patients in Asia and patients who underwent combination therapy with programmed cell death-1 and cytotoxic T-lymphocyte-associated antigen 4 inhibitors demonstrated significantly higher frequency of ophthalmoplegia than other ocular irAEs." (PMID 34504488, 2021).